BAP1 (BRCA1 associated deubiquitinase 1)
Diseases named in the same sentence as BAP1 in open-access papers (continued):
Sharing a sentence is not in itself a finding about the gene and the disease.
uveal melanoma (continued). "Therefore, BAP1 screening could be a useful approach for identifying uveal melanoma predisposition, whereas the immunohistochemistry technique has been used as a solid method for prognostic purposes." (PMID 31109147, 2019). "While BRAF and NRAS mutation are the most two common mutations in cutaneous melanoma, BAP1 mutation frequently occurs in uveal melanomas exclusively with BRAF or NRAS mutations 146, suggesting that BAP1 mutation may be a specific genetic marker for uveal melanoma." (PMID 28544818, 2017). "This could represent a possible connection between BAP1 and expression of HLA in uveal melanoma, as study in mice showed that loss of BAP1 leads to increased levels of EZH2 (and PRC2) with repressed expression of its targets, including thus CIITA, leading ultimately to less HLA class II expression." (PMID 27764126, 2016). "Inactivating mutations in BRCA1-associated protein 1 (BAP1) are observed in approximately 45% of primary and ~85% of metastatic uveal melanoma (UM) cases and are strongly correlated with aggressive phenotypes and poor prognosis." (PMID 41726922, 2026). "Intriguingly, these genes were all remarkably decreased in BAP1-null uveal melanoma cells as compared with BAP1 WT cells." (PMID 39817454, 2025). "Cytoplasmic expression of BAP1 has been described in a subset of uveal melanomas, suggesting a functional role of BAP1 within the cytoplasm that warrants further investigation." (PMID 39268598, 2025). "However, it is again critical to note that BAP1 mutations are more prevalent and have greater prognostic relevance in uveal melanoma compared to cutaneous melanoma, suggesting that the therapeutic potential of Niraparib in cutaneous melanoma may be more limited." (PMID 40842586, 2025). "To dissect how BAP1 impacts the tumor-suppressive transcriptional program in cancer cells, we examined 4 different human uveal melanoma cell lines including BAP1 WT (MP41) and null cells (MP38, MP46, and MP65)." (PMID 39817454, 2025). "The first mutation set encompasses the eight UM driver genes according to the TCGA study, divided into “uveal melanoma initiating mutations” (CYSLTR2, GNA11, GNAQ and PLCB4) and “second hit mutations with prognostic impact” (BAP1, EIF1AX, SF3B1 and SRSF2)." (PMID 39858540, 2025). "Of note, this group of genes included drivers for uveal melanoma, such as BAP1 paired with other genes." (PMID 40615675, 2025). "The second patient had a personal history of cutaneous melanoma, a family history of cutaneous and uveal melanoma, and over 7 years of follow‐up, developed four additional BAP1‐inactivated melanocytic tumours (BIMTs) confirmed by IHC." (PMID 39976080, 2025). "Studies beyond the scope of the present manuscript will be required to fully understand the regulation of BAP1 and the Hippo pathway in uveal melanoma cells." (PMID 38758815, 2024). "In uveal melanoma, MITF loss is associated with loss of BAP1 protein expression, which is another stemness biomarker associated with poor prognosis." (PMID 38539487, 2024). "The loss of chromosome 3 and mutations of the Ubiquitin Carboxyl terminal Hydrolase gene (BAP1) are strictly related to the progression of uveal melanoma." (PMID 38732371, 2024). "In summary, BAP1 has proven to reliably predict the likelihood of disease progression in uveal melanoma, while further studies are needed to establish the significance of other driver mutations." (PMID 39061150, 2024). "Extensive research has uncovered recurrent genetic alterations in uveal melanoma, with mutations in SF3B1, BAP1, CYSLTR2, GNAQ, GNA11, and PLCB4 being particularly prevalent." (PMID 38724687, 2024). "While BAP1’s role as a tumor suppressor is well-established in breast cancer, malignant mesothelioma, and uveal melanoma, its involvement in targeted therapy-induced apoptosis is novel." (PMID 39709491, 2024).
uveal melanoma (continued). "Three different research groups looking at MPM, cutaneous melanoma, and uveal melanoma discovered the BAP1 tumor predisposition syndrome (BAP1-TPDS), MPM, cutaneous melanoma, and uveal melanoma." (PMID 39407894, 2024). "This meta-analysis aimed to evaluate the prognostic significance of driver mutations, including GNAQ, GNA11, BAP1, and SF3B1, in the advancement of uveal melanoma." (PMID 39061150, 2024). "Germline BAP1 mutations cause the BAP1 predisposition syndrome (BAP1-TPDS), associated with a high susceptibility to various malignancies, such as uveal melanoma, malignant mesothelioma, cutaneous melanoma, renal cell carcinoma, and other tumors." (PMID 38903495, 2024). "Loss of chromosome 3 and mutations of the Ubiquitin Carboxyl terminal Hydrolase gene (BAP1) are strictly related to the progression of uveal melanoma." (PMID 38732371, 2024). "They noted that 31% (54/174) of BAP1 carriers were diagnosed with a uveal melanoma, 22% (39/174) had a malignant mesothelioma (26/39 of which were pleural), 13% (23/174) of cases had a cutaneous melanoma and 10% (18/174) had renal cell carcinoma." (PMID 37607989, 2023). "Although most significant in MPM, inverse correlation was evident in the other cancers with common BAP1 inactivation (cholangiocarcinoma, uveal melanoma, and RCCC) but relatively uncommon among other cancers, suggesting cell context specificity." (PMID 36669126, 2023). "Melanoma ex blue nevus or a malignant melanoma which arises within a pre-existing blue nevus has been shown to lack expression of the BAP1 gene and likely plays a role in the pathogenesis similarly to the mechanisms seen in uveal melanoma." (PMID 38090659, 2023). "The goal of the study presented here was to apply this strategy for differential diagnosis of BAP1-TPDS in patients with uveal melanoma." (PMID 35920959, 2023). "While cutaneous melanoma is often characterized by BRAF, NRAS and KIT mutations, uveal melanoma typically harbors GNAQ/GNA11, EIF1AX, SF3B1, BAP1 mutations and chromosomal abnormalities." (PMID 36674809, 2023). "Germline BAP1 mutation underpins a cancer predisposition syndrome where family members develop multiple cancers, most commonly MPM, peritoneal mesothelioma, and uveal melanoma." (PMID 36669126, 2023). "Knockdown of E-cadherin and cell adhesion molecule 1-related genes decreased cell growth, migration, and cell-to-cell adhesion of BAP1-mutant uveal melanoma cells." (PMID 38069077, 2023). "Familial uveal melanoma is far more likely to be due to BAP1 GPV than sporadic cases with a pick up rate of 25%." (PMID 37607989, 2023). "Epigenetic changes downregulating PD-L1 and other key immune checkpoints, including LAG-3 and CTLA-4, have been observed in uveal melanoma with BAP1 disruption." (PMID 36674809, 2023). "Up to 40% of uveal melanomas metastasize hematogenously, primarily to the liver, and BRACA1-associated protein 1 (BAP1) mutations cause loss of function, as well as type 2 gene expression profiles, are associated with uveal melanoma dissemination and death." (PMID 35804893, 2022). "It is well known that a somatic mutation causing inactivation of BAP1 (encoding BRCA1-associated protein 1; located on chromosome 3) in uveal melanoma cells was prognostically unfavourable." (PMID 35681733, 2022). "Another mutation that is reported to increase the risk of uveal melanoma and thyroid carcinoma is BRCA-1 associated protein (BAP1)." (PMID 35039080, 2022). "This included BAP1 mutant uveal melanoma lines (MM28, MP46, and MP38), a molecular change strongly associated with liver metastasis." (PMID 35804893, 2022). "Our findings provide a functional explanation for the observed mutual exclusivity of BAP1 and SF3B1 mutations in uveal melanoma." (PMID 34706158, 2022).
uveal melanoma (continued). "Loss of function mutations in BAP1, gain of function mutations in related EIF1AX and SF3B1, and chromosomal 8q gains have been identified as secondary driver mutations in uveal melanomas and are present in a subset of malignant blue nevi." (PMID 35008286, 2021). "Inactivating BAP1 mutants were found in two patients with uveal melanoma by exon capture and large‐scale sequencing, and BAP1 mutants were also found in 25 (45%) of 55 additional cases of uveal melanoma." (PMID 33529461, 2021). "The E2F1 targets pathway was involved in the BAP1-mediated cell cycle progression of uveal melanoma cells." (PMID 34434692, 2021). "The sample size of this study is too small to reliably investigate the role of BAP1 alternation and SF3B1 mutations in survival of metastatic uveal melanoma patients and this remains to be investigated in future studies." (PMID 34830903, 2021). "In this paper, we therefore investigate how the proportion of BAP-1 positive cells varies across the cut surface of uveal melanomas, and the prognostic weight of different tumor regions." (PMID 33800007, 2021). "Our results confirm the remarkable prognostic value in analysis of BAP-1 expression in uveal melanoma." (PMID 33800007, 2021). "The main objectives of this study were to discover the clinical and histological features of uveal melanoma in a regional Spanish community and to evaluate the application of BAP1 immunohistochemistry staining in this group." (PMID 34771510, 2021). "In this study, we investigate the intratumor heterogeneity of BAP-1 expression in uveal melanoma with digital image analysis of 40 tumors." (PMID 33800007, 2021). "Germline BAP1 loss is associated with earlier onset MPM tumours, as well as other BAP1-related malignancies such as uveal melanoma." (PMID 34209209, 2021). "BAP1 was also reported to exert its tumor suppressor function through the Hippo pathway that plays a key role in uveal melanoma." (PMID 33800394, 2021). "HDAC inhibitors have been found to help reverse the effect of losing BAP-1 in uveal melanoma in vitro and shown to decrease metastasis rates." (PMID 34298647, 2021). "Typical uveal melanoma-related mutations were found in seven cases (15%): one case with GNAQ p.R183Q, one with GNA11 p.R183C, two with SF3B1 p.R625C/H, and three with BAP1 missense/nonsense supposedly somatic mutations." (PMID 34359736, 2021). "In this paper, the intratumor heterogeneity in uveal melanoma BAP-1 expression is investigated for the first time." (PMID 33800007, 2021). "In conclusion, to the best of our knowledge, this is the first time that BAP1 staining has been studied in uveal melanoma in a Spanish community." (PMID 34771510, 2021). "We have shown that there is substantial intratumor heterogeneity in uveal melanoma BAP-1 expression." (PMID 33800007, 2021). "Uveal melanoma has been thought to result from an initiating GNAQ/GNA11 mutation, followed by a secondary BSE event from mutations in the genes BAP1, SF3B1, and EIF1AX." (PMID 32429485, 2020). "In uveal melanoma, GNAQ and GNA11 gene mutations are frequently found and prognosis is based on mutation status of BAP1, SF3B1 and EIF1AX genes." (PMID 33396957, 2020). "Germline mutations in BAP1 causes a predisposition syndrome with increased risk to renal cell carcinoma, MPM and uveal melanoma." (PMID 33072611, 2020). "BAP1 is a tumor suppressor gene important to the development and prognosis of many cancers, especially uveal melanoma (UM)." (PMID 30716094, 2019). "In our study, we used a patch-based method to settle the resolution issue and cropped the image into unified 256 × 256 patches for the classification of uveal melanoma BAP1 expression." (PMID 31623293, 2019). "In uveal melanoma cells, depletion of BAP1 resulted in a 20–40% reduction in cell cycle progression; however, it seems that this change was of a transient nature." (PMID 30669483, 2019).
uveal melanoma (continued). "We conclude that this deep learning model provides an accurate and reproducible method for the prediction of BAP1 expression in uveal melanoma." (PMID 31623293, 2019). "BAP1 binds to E2F1-responsive gene promoters through HCF-1 and upregulates their expression, and BAP1 KO inhibits the growth of uveal melanoma cells." (PMID 30389914, 2018). "Germline mutations in BAP1 have been associated with BAP1-Tumor Predisposition Syndrome (BAP1-TPDS), a predisposition to multiple tumors within a family that includes uveal melanoma (UM), cutaneous melanoma, malignant mesothelioma and renal cell carcinoma." (PMID 30477459, 2018). "We have used the “Calling Card System” of transposase-directed transposon insertion mapping to identify the genomic targets of BAP1 in uveal melanoma (UM)." (PMID 30400891, 2018). "Partial or complete monosomy of chromosome 3, where BAP1 (3p21.31-p21.2) is located, is a relatively common event in metastasizing uveal melanoma." (PMID 29769598, 2018). "Uveal melanomas, in contrast to conjunctival melanomas, lack BRAF or NRAS mutations but frequently have mutations in GNAQ, GNA11, BAP1, SF3B1 or EIF1AX." (PMID 28938534, 2017). "Koopmans and others found strong correlations between the BAP1 IHC and sequencing data in uveal melanoma." (PMID 28404968, 2017). "In uveal melanoma cell lines, HDAC inhibitors partially rescue the loss of melanocytic differentiation associated with BAP1 depletion." (PMID 25970771, 2015). "BAP1 is a tumor suppressor gene that is lost or deleted in diverse cancers, including uveal mela¬noma, malignant pleural mesothelioma (MPM), clear cell renal carcinoma, and cholangiocarcinoma." (PMID 25830670, 2015). "Germline BAP1 mutation underpins a cancer predisposition syndrome and BAP1 protein expression is reportedly lost in around 50% of NSCLC, colon carcinoma, uveal melanoma and kidney cancers." (PMID 25970771, 2015). "Uveal melanoma most frequently carry mutations in the GNAQ, GNA11, and BAP1 genes, where GNAQ/GNA11 mutations are mutually exclusive." (PMID 25106493, 2014). "Prompted by these transcriptomic findings, we wished to explore further the possibility that BAP1 inhibits metastasis of uveal melanoma cells by maintaining their differentiated state and impeding their reversion to a stem-like state." (PMID 23915344, 2013). "As this interaction has not been addressed within the melanocytic lineage, we examined the interaction between endogenous BAP1 and HCF-1 in BAP1-wildtype uveal melanoma cells." (PMID 23915344, 2013). "In this report, we studied the effects of both transient and stable RNAi-mediated depletion of BAP1 in uveal melanoma cells." (PMID 23915344, 2013). "The uveal melanoma cells stably expressing shRNA against BAP1 and control shRNA against GFP were compared using in vitro and in vivo assays of tumorigenicity." (PMID 23915344, 2013). "In uveal melanoma a different set of genes shows recurrent mutations, including GNAQ and GNA11, with activating mutations as well as in BAP1 showing inactivating mutations." (PMID 23694694, 2013). "As the majority of uveal melanomas metastasize to the liver, it will be exciting to see if BAP1 is involved in regulation of metastasis specifically to this site." (PMID 24212610, 2010). "Although not routinely used, genetic markers such as BAP1 mutations in uveal melanoma can also provide valuable prognostic insight." (PMID 41341795, 2026). "Finally, we analyzed the RNA-Seq data from an independent study in which WT BAP1 was reexpressed in uveal melanoma UM22 (BAP1 null) cell lines." (PMID 39817454, 2025). "In our cohort of primary uveal melanomas from vfDNA+/UM+ patients, BAP1 alterations occurred throughout the entire gene, most of the SF3B1 mutations affected position p.R625, and EIF1AX mutations were found at various positions within the first two exons of the gene." (PMID 40240901, 2025).
uveal melanoma (continued). "In uveal melanoma (UM), despite the complex cell composition within individual tumors, class 2 tumors such as UMM061, UMM063 and UMM064 are associated with high metastatic risk and inactivating mutations in BAP1." (PMID 40478912, 2025). "A study indicated that metastasized uveal melanomas exhibited mutations in GNAQ and BAP1." (PMID 40598734, 2025). "The absence of BRCA-1-associated protein 1 (BAP1) expression and monosomy 3 in uveal melanoma are known to be associated with metastatic progression and poor survival." (PMID 41464321, 2025). "Thus, we determined the impact, if any, of GZ17-6.02, afatinib and neratinib upon the expression of BAP1 in our uveal melanoma isolates." (PMID 38758815, 2024). "Uveal melanoma (UM) cells are characterized by the presence/absence of BAP1 protein and mutation in the GNAQ/GNA11 genes." (PMID 39195238, 2024). "Inactivation of BAP1 expression by BAP1 methylation, as has been observed in some uveal melanoma cases, could also be a contributing factor." (PMID 39091916, 2024). "Therefore, we performed long-term colony formation assays in human uveal melanoma cell lines with different BAP1 status." (PMID 38054839, 2024). "Non-uveal BAP1 mutated melanomas frequently exhibited UV-signature mutations and had a significantly higher mutation load than uveal melanomas." (PMID 38903495, 2024). "BAP1 mutations are associated with poor prognosis in uveal melanoma, but their prognostic value in non-uveal melanoma remains controversial." (PMID 38903495, 2024). "However, in non-uveal melanoma, the role of BAP1 in tumorigenesis and its prognostic significance, particularly in cutaneous melanoma, has been controversial." (PMID 38903495, 2024). "Based on links to AEBP2, EZH2, and RA signaling, and knowing that BAP1 mutations reduce SOX10 and EDNRB levels in uveal melanoma, we initially hypothesized that ENS Bap1 loss would cause distal bowel aganglionosis, the defining feature of HSCR." (PMID 38690732, 2024). "Mutation of BAP1 can also result in alterations to histone methylation, and we further explored whether GZ17-6.02 changed the methylation of Histone H3 in uveal melanoma cells." (PMID 38758815, 2024). "This highlights that although BAP-1 is a very strong prognostic indicator, it’s presence or absence varies between studies, and that other factors can drive the metastatic progression of uveal melanoma." (PMID 37117276, 2023). "The metastatic risk of uveal melanoma (UM) is defined by a limited number of molecular lesions, somatic mutations (SF3B1 and BAP1), and copy number alterations (CNA): monosomy of chromosome 3 (M3), chr8q gain (8q), chr6p gain (6p), yet the sequence of events is not clear." (PMID 37958591, 2023). "Remarkably, around one third of families with both cases of cutaneous and uveal melanomas display mutations in BAP1, as opposed to families with multiple cutaneous melanomas alone, in which they are detected in less than 1% of the cases." (PMID 37568588, 2023). "BAP1 methylation has been identified as a prognostic indicator of uveal melanoma spread." (PMID 37124608, 2023). "Previous research in uveal melanoma demonstrated that BAP1 could regulate the expression of multiple cell adhesion molecules." (PMID 35941663, 2022). "In the sequence of mutations, the BAP-1 mutation has been assumed to occur relatively late, preceded by smaller genomic alterations in G-protein subunits including GNA11 or GNAQ that are present in virtually all uveal melanomas." (PMID 33800007, 2021). "Regardless of region, analysis of BAP-1 expression adds significant prognostic value to both tumor size category and gene expression class, adding to the notion that uveal melanoma BAP-1 immunohistochemistry is one of the very strongest prognostic tests in any malignancy." (PMID 33800007, 2021).